BMS1 (BMS1 ribosome biogenesis factor)
Description:
GTPase required for the synthesis of 40S ribosomal subunits and for processing of pre-ribosomal RNA (pre-rRNA) at sites A0, A1, and A2. Controls access of pre-rRNA intermediates to RCL1 during ribosome biogenesis by binding RCL1 in a GTP-dependent manner, and delivering it to pre-ribosomes. GTP-binding and/or GTP hydrolysis may induce conformational rearrangements within the BMS1-RCL1 complex allowing the interaction of RCL1 with its RNA substrate. Required for RCL1 import into the nucleus.
Synonyms: BMS1L; KIAA0187; ACC
Tractability: Small molecule: a structure with a bound ligand is known. PROTAC: UniProt records ubiquitination sites on it; ubiquitination databases record sites on it; its protein half-life has been measured.
Gene: Protein-coding gene on chromosome 10 (42,782,783 to 42,834,937, forward strand). Ensembl gene ENSG00000165733.
Subcellular location: Nucleus, nucleolus
Subcellular location (Human Protein Atlas): Mitotic chromosome; Nucleoli; Nucleoplasm
Pathways (Reactome):
Metabolism of RNA: Major pathway of rRNA processing in the nucleolus and cytosol; rRNA modification in the nucleus and cytosol
Gene Ontology:
Molecular function: protein binding; RNA binding; GTPase activity; GTP binding
Biological process: ribosomal small subunit biogenesis; endonucleolytic cleavage of tricistronic rRNA transcript (SSU-rRNA, 5.8S rRNA, LSU-rRNA); maturation of SSU-rRNA; maturation of SSU-rRNA from tricistronic rRNA transcript (SSU-rRNA, 5.8S rRNA, LSU-rRNA); ribosome biogenesis
Cellular component: chromosome; nucleolus; nucleoplasm; small-subunit processome; 90S preribosome; nucleus; preribosome
Genetic constraint (gnomAD): Loss-of-function variants: 52 observed, 129.25 expected, observed/expected ratio (o/e) 0.4, 90% interval 0.32 to 0.51. The upper end of that interval is the gene's LOEUF score, 0.51, which puts it in group 2 of 6, group 1 being the genes least tolerant of losing a copy. Missense variants: 1,306 observed, 1,493.6 expected, observed/expected ratio (o/e) 0.87, 90% interval 0.83 to 0.92. Synonymous variants: 487 observed, 522.88 expected, observed/expected ratio (o/e) 0.93, 90% interval 0.86 to 1.
Homologues: Orthologues: chimpanzee BMS1 (99% identical), macaque BMS1 (95% identical), pig BMS1 (92% identical), dog BMS1 (90% identical), rabbit BMS1 (88% identical), mouse Bms1 (87% identical), guinea pig BMS1 (86% identical), rat Bms1 (86% identical), tropical clawed frog bms1 (69% identical), zebrafish bms1 (61% identical), Drosophila melanogaster CG7728 (44% identical), Caenorhabditis elegans Y61A9LA.10 (41% identical). Paralogues in human: TSR1 (14% identical).
Diseases named in the same sentence as BMS1 in open-access papers:
BMS1 is named in the same sentence as 13 diseases in open-access papers, as found by Europe PMC text mining. Sharing a sentence is not in itself a finding about the gene and the disease. The quoted sentences say what the papers report.
breast carcinoma (1 paper, 2020). "The focal CNAs contained several cancer relevant genes, such as the known breast cancer genes EGF, CDKN2A and BAG1 and some were less established including ZAR1 and BMS1." (PMID 33168853, 2020).
cervical carcinoma (1 paper, 2021). A carcinoma arising from either the exocervical squamous epithelium or the endocervical glandular epithelium. "The increased sample size enabled identification of SMGs previously unreported in cervical carcinoma including NBPF10 (8%), RANBP2 (6%), MSN (6%), KRT8 (6%), POTEC (6%), ZC3H11A (4%), BMS1 (4%), GPX1 (3%), OTOP1 (3%), DNAH12 (2%), COIL (2%), TBC1D26 (2%), SPRED3 (2%), FAM115A (2%), and ARIH1 (1%)." (PMID 34620846, 2021).
epilepsy (1 paper, 2018). A brain disorder characterized by episodes of abnormally increased neuronal discharge resulting in transient episodes of sensory or motor neurological dysfunction, or psychic dysfunction. "BMS1 is a ribosome biogenesis factor already reported to be involved in epilepsy." (PMID 29958461, 2018).
osteoarthritis (1 paper, 2025). A noninflammatory degenerative joint disease occurring chiefly in older persons, characterized by degeneration of the articular cartilage, hypertrophy of bone at the margins and changes in the synovial membrane. "Several other genes are implicated in DDH but currently have a sparse association with human osteoarthritis in the literature, including BMS1, HOXD9, TBX4, TENM3, and PAPPA2." (PMID 41019141, 2025). "Several other genes implicated in DDH and/or FAI but with a sparse association with human osteoarthritis in the literature, including BMS1, HOXD9, TBX4, TENM3, PAPPA2, and HOXB9, should be further investigated to elucidate their role in osteoarthritis development." (PMID 41019141, 2025).
tumor (2 papers, 2020 to 2022). "The 5hmC levels and gene expression of BMS1 and GEMIN5 are both reduced in AML compared to controls, supporting the tumor suppressor nature of these genes." (PMID 35859008, 2022).
infection (1 paper, 2010). The state of being infected such as from the introduction of a foreign agent such as serum, vaccine, antigenic substance or organism. "This was supported by immunostaining for the nucleolar proteins fibrillarin and BMS-1, which remained unaltered following infection." (PMID 20585567, 2010).
BMS1 also shares sentences with these, for which no sentence is quoted: cancer (1 paper); Cirrhosis (1); developmental delay (1); hypovitaminosis D (1); melanoma (1); prostate carcinoma (1); rubella (1).